CD69 (CD69 molecule)
Diseases named in the same sentence as CD69 in open-access papers (continued):
Sharing a sentence is not in itself a finding about the gene and the disease.
non-small cell lung carcinoma (8 papers, 2018 to 2024). A group of at least three distinct histological types of lung cancer, including non-small cell squamous cell carcinoma, adenocarcinoma, and large cell carcinoma. "Costimulatory molecules expressed by most CD8+ TRM cell subsets are CD27 and CD28, and in non-small cell carcinoma, the CD69+CD8+ TILs express CD27 and CD28." (PMID 33467606, 2021). "Deletion of CD69 was reported in non-small-cell lung cancer and lymph node metastasis." (PMID 35652109, 2022). "In addition, the research on T-cell showed that co-expression of PD-1, LAG-3 and TIM-3 was associated with prominent activation (CD69 expression) and effector function (GZMB level), as well as elevated levels of proapoptotic markers in non-small cell lung cancer." (PMID 39767624, 2024). "Immune profiling studies on non-small cell lung cancer (NSCLC), renal cancer and melanoma PDOs demonstrated retention of CD8+ and CD4 + T cells, CD14/CD69+ macrophages, NK and NKT cells and B cells." (PMID 37438470, 2023). "In non-small cell lung carcinoma, CD103+CD8+ T cells co-express CD49a and CD69 and display a molecular profile characterized by the expression of PD-1 and the ectonucleotidase CD39." (PMID 33467606, 2021). "In line with this, non-small cell lung cancer (NSCLC) express high CXCL12 levels and especially recruits CD4+CD69+CXCR4+ T cells with an increased ratio of regulatory T cells." (PMID 30319622, 2018).
tuberculosis (8 papers, 2011 to 2024). A chronic, recurrent infection caused by the bacterium Mycobacterium tuberculosis. "For example, CD69 is a co-stimulatory receptor and a marker of early T-cell activation, and elevated levels of CD4+, CD69+, IFN-γ+ T cells are associated with early active or recent tuberculosis." (PMID 37686061, 2023). "Our data indicate a decreased capacity for activation of helper T lymphocytes in patients with active tuberculosis, represented by the lowest percentage of CD69+ cells." (PMID 26000298, 2015). "In the present study, we found that without any stimulation, CD4+ T cells in pleural fluid cells (PFCs) from patients with TBP expressed significantly higher levels of CD69 than PBMCs from patients with tuberculosis (TB) or healthy donors." (PMID 21887301, 2011).
Allergy (7 papers, 2013 to 2023). An allergy is an immune response or reaction to substances that are usually not harmful. "Taking this into consideration alongside the allergy-associated constitutive presence of cytokines in plasma and spontaneous release of soluble molecules during in vitro culture, we looked for the expression of CD69, a leukocyte activation molecule expressed in situations of chronic inflammation." (PMID 38067164, 2023). "Interestingly, loss of CD69+ cells has also been associated with exacerbated allergic disease." (PMID 23349887, 2013). "The surface expression of CD63, CD203c and CD69 is commonly used to assess human basophil activation upon acute hypersensitivity allergic reaction." (PMID 36685514, 2022). "For instance, monocyte subpopulations showed higher levels of CD371 (inhibitory receptor) and CD69 (early activation marker) in both allergy groups and with simultaneously decreased CD23 (low affinity IgE receptor) expression only in the IgEneg allergy group." (PMID 32698761, 2020).
chronic lymphocytic leukemia (7 papers, 2016 to 2023). "Multiple hemopoietic cells express CD69, which serves as an early activation marker in chronic lymphocytic leukemia." (PMID 37810000, 2023). "Our results correspond with evidence found in chronic lymphocytic leukemia, where the expression of CD69 also predicted a shorter duration of response and survival." (PMID 37653425, 2023). "It significantly decreased tumor proliferation and expression of surface activation markers CD69 and CD86 in chronic lymphocytic leukaemia which has similar clinical manifestations to MCL." (PMID 32685149, 2020).
liver cancer (7 papers, 2021 to 2025). An epithelial or non-epithelial malignant neoplasm that arises from the liver. "Relevant to liver cancer, a positive impact of DC vaccines on NK cells, characterized by increased expression of the activation markers CD25 and CD69 on circulating NK cells, was also reported in murine models of liver cancer and in HCC patients." (PMID 34062821, 2021). "In human liver cancer, however, NK cells in the peri-tumoral stroma where they co-localize with TAMs express an activation marker CD69 more frequently than NK cells in the TAM-sparse intra-tumoral region, which implies that TAMs promote NK cell function under certain circumstances." (PMID 37313600, 2023). "It is also reported that expression of NK cell activation markers (e.g., CD69, TRAIL, granzyme B) is increased by short-term (2 days) exposure to TAMs from human liver cancer, whereas long-term (8 days) exposure decreases." (PMID 37313600, 2023). "It was noted that memory CD4 T cells (CD4+CD69+) were enriched in liver cancers with low clonality, while proliferative pre-exhausted CD4 T cells (CD4+MKI67+CXCL13+) were enriched liver cancers with high clonality and a major source of cytokines and chemokines." (PMID 36980203, 2023). "Moreover, the expression of the activation markers CD25 and CD69 on CD8+ T cells decreased when the cells were cocultured with TANs but not non-TANs, thus suggesting that liver cancer TANs directly inhibited CD8+ T cell activation." (PMID 37184030, 2023).
myocarditis (7 papers, 2015 to 2025). Myocarditis is a condition that is characterized by inflammation of the heart muscle (myocardium). "TCR sequencing revealed expansions of CD8 GZMK + GZMA + and CD8 PRF1 + GZMA + T cells in myocarditis patients, along with increased activation markers CD69 and KLRG1, supporting the idea that specific cytotoxic CD8 T cell groups promote inflammation." (PMID 41510228, 2025). "While the frequency of CD69+ NK cells in blood correlated with myocarditis-specific symptoms of chest pain (ρ=0.269), the frequency of HLA-DR+ monocytes correlated with non-specific febrile reaction instead (ρ=0.442; p=0.001, lower panel)." (PMID 40046048, 2025). "Notably, cluster 10 was more prevalent in patients exhibiting high-grade myocarditis and, similar to our initial data, this cluster also showed a high level of CD69 expression." (PMID 41510228, 2025). "In this study, we found that the four highest ranking cytokines that were most associated with hypovitaminosis D were exactly these 4 cytokines, strongly supporting the hypothesis that vitamin D plays role in this myocarditis-specific cytokine profile pivotal for early activation of CD69+ NK cells." (PMID 40046048, 2025). "Studies have shown that neutralizing IL-17 or inhibiting its signaling pathways can reduce the severity of myocarditis and improve cardiac function in animal models In EAM, CD69 negatively regulated cardiac inflammation through control of heart-specific Th17 responses." (PMID 39817455, 2025). "Overall, these results confirm the central role of NK cells in mediating the specific symptoms of BNT162b2 vaccine-related myocarditis and highlight the immunoregulatory role of vitamin D in modulating the specific CD69+ NK cell subset but not the non-specific monocyte-mediated febrile reaction." (PMID 40046048, 2025).
atopic dermatitis (6 papers, 2018 to 2025). "The results indicate a significant decrease in MAIT cells and CD69 subsets in atopic dermatitis, coupled with elevated CD38 and polyfunctional MAIT cells producing TNFα and Granzyme B (TNFα+/GzB+)." (PMID 38542456, 2024). "CD69-expressing NKT cells, which resemble tissue-resident memory (TRM) cells, are implicated in allergic conditions like atopic dermatitis." (PMID 39451246, 2024). "In regards to activation, increased CD69 expression occurred specifically in the peripheral blood and splenic eosinophils in T. canis-infected animals, corroborating with Titz that demonstrated an increase of CD69 expression in peripheral blood eosinophils from patients with atopic dermatitis." (PMID 29445372, 2018). "In fact, in atopic dermatitis, eosinophils displayed no change in surface CD125, which also did not correlate with CD69 but was associated instead with CD44 and HLA-DR." (PMID 40710346, 2025).
breast tumors (6 papers, 2018 to 2024). "DC3s efficiently induce differentiation of CD103+CD8+ T cells in vitro, and their infiltration correlates with CD8+CD69+CD103+ TRM accumulation in breast tumors." (PMID 32610077, 2020). "Finally, we show that DC3s activate CD103+ T cells and that DC3 infiltration in human breast tumors correlates with the abundance of CD8+CD103+CD69+ tissue-resident memory (TRM) T cells." (PMID 32610077, 2020). "A substantial proportion of the CD8+ T cells in breast tumors are TRM (38%;), defined by the expression of CD103 and CD69." (PMID 33467084, 2021). "Both CD103 and CD69 limit T cell tissue egress by downregulation of several chemotaxis regulators (e.g., S1RP1 and KLF2) and receptors (KLRG1) and are crucial determinants of TRM retention in epithelial tissues, including breast tumors." (PMID 33467084, 2021).
colon carcinoma (6 papers, 2014 to 2025). "Recent work on CD69 immuno-PET in a murine colon carcinoma model demonstrated an association between tracer uptake and response to ICI, further supporting the use of CD69 immuno-PET for immunotherapy response assessment in GBM." (PMID 37426447, 2023). "Likewise, αPD-1 induced accumulation of mature (CD62L–) and cytotoxic (CD69+GZMB+) NK cells in the MC38 colon cancer model." (PMID 40530504, 2025). "This is further supported by recent work on a murine colon carcinoma model that showed radiolabeled CD69-directed Ab combined with PET imaging as a noninvasive method to assess the early response to ICI with increased uptake in the tumors and lymphoid tissue of ICI-responsive tumor-bearing mice." (PMID 37426447, 2023). "We therefore determined whether IL-7, and/or OXP treatment enhanced the presence of activated CD8+ T cells (CD8+CD69+ population) in the two models murine colon tumors." (PMID 24465710, 2014). "In primary colon cancer, the expression of CD69, an indicator of CD4+ T-cell activation, was not significantly affected by αPD-1 or Re-FMT." (PMID 40191185, 2025).
endometriosis (6 papers, 2006 to 2023). The growth of functional endometrial tissue in anatomic sites outside the uterine body. "We found PF-specific endometriosis-associated immune signatures from both innate and adaptive immune lineages, underlined by distinct phenotypes that were marked by CD69." (PMID 31907005, 2020). "The study offers a systematic view of immune cell signatures found in the peritoneal cavity and reveals CD69+ T cell populations that are associated with endometriosis." (PMID 31907005, 2020). "Expression of the pleiotropic immune activation marker CD69, a member of the C-type lectin superfamily, is specifically increased on T cells in PF, which we identified as a major T cell signature in the peritoneal environment associated with endometriosis." (PMID 31907005, 2020). "Therefore, CD69 identifies T cells with a distinct phenotype across lineages in the peritoneal cavity associated with endometriosis." (PMID 31907005, 2020). "Consistent with platelet-induced CD69+ T cell activation, there is an increase in CD69+ T cells in the peritoneal fluid from women with endometriosis and possibly in adenomyosis as well." (PMID 36769489, 2023). "We validated the expression of CD69 on T cells by manual gating, confirming a specific increase of CD69-expressing T cells in PF from endometriosis patients." (PMID 31907005, 2020). "Given the specific increase of CD69 on PF T cells, we wanted to know if there is any difference on the CD69+ population in PF and blood from endometriosis and control samples." (PMID 31907005, 2020). "PCA of expression values of markers differentiates PF CD69+ cells from blood CD69+ cells, although control and endometriosis CD69+ cells are alike." (PMID 31907005, 2020). "This suggests that CD69 is a novel and major signature correlated with endometriosis in the peritoneal environment." (PMID 31907005, 2020). "CD69 antigen expression was on comparable levels in ovarian and scar endometriosis, while in ovarian endometriosis it was significantly higher than in the control group." (PMID 16907986, 2006). "There is some evidence of upregulated activation marker CD69 expression on peritoneal fluid T cells in endometriosis patients, although it is important to emphasize that the investigated cohort had been taking hormonal treatment hence this study was not included in our systematic review." (PMID 37497226, 2023). "The level of CD69+ eosinophil occurred to be high in the peritoneal fluid of endometriosis patients, indicating that activated eosinophils accumulated in the early stages of endometriosis and played an important role in endometriosis pathogenesis." (PMID 35303800, 2022). "Thus, our comparison of control and endometriosis samples reveals that the T cell activation marker CD69 is uniquely upregulated in PF samples." (PMID 31907005, 2020). "Notably, among the inflammatory microenvironment in peritoneal fluid (PF), the presence of CD69+ T cell subsets is increased in endometriosis when compared to control patient samples." (PMID 31907005, 2020). "Similarly, CD69 antigen expression was significantly higher in scar endometriosis than in the control group." (PMID 16907986, 2006). "However, increased CD69 expression on CD56+ cells in PF from endometriosis has been reported." (PMID 31907005, 2020). "This separation was driven in part by the expression of CD69, suggesting that CD69 may not be a suitable blood biomarker for endometriosis." (PMID 31907005, 2020). "The significance of CD69 expression by T cells in endometriosis has not yet been determined." (PMID 31907005, 2020). "We next compared the expression levels of functional markers on T cell subsets and found that whereas phenotype of CD69 populations in control and endometriosis samples was not differentiable, CD69+ cells show significantly distinct expression levels of these markers from CD69− populations." (PMID 31907005, 2020).
head and neck squamous cell carcinoma (6 papers, 2019 to 2025). A squamous cell carcinoma that arises from any of the following anatomic sites: lip and oral cavity, nasal cavity, paranasal sinuses, pharynx, larynx, and salivary glands. "High levels of tumor infiltrating activated CD4+ CD69+ T cells are associated with better locoregional control and improved survival in Head and Neck Squamous Cell Carcinoma patients." (PMID 33211709, 2020). "On the contrary, high levels of tumor-infiltrating CD4+CD69+ T cells are associated with good prognosis in head and neck squamous cell carcinoma." (PMID 31649887, 2019). "Comparison of percentages of subtypes and expression of the CD69 activation marker between patients with head and neck squamous cell carcinoma and healthy volunteers." (PMID 40802351, 2025). "EVs with high expression of PD-L1 in head and neck squamous cell carcinoma significantly inhibited CD69 on CD8+ T cells and inhibited T cell activation." (PMID 40760673, 2025). "Comparison by median fluorescence intensity of immune cell subtypes and expression of the CD69 activation marker between patients with head and neck squamous cell carcinoma and healthy volunteers." (PMID 40802351, 2025). "In head and neck squamous cell carcinoma, the group with high activated CD4(+)CD69(+) T cells had a better prognosis than the group with low CD4(+)CD69(+) T cells." (PMID 37033978, 2023).
Hepatitis (6 papers, 2014 to 2022). Inflammation of the liver. "In our study, Patients with AHB and CHB had a significant higher frequency of CD69+CD8+ T lymphocytes compared with IT patients, which may suggest that the occurrence of hepatitis is linked to increased proportion of activated CD8+ T lymphocytes." (PMID 36353632, 2022). "For example, the predominant TRM cells associated with the pathogenesis of AIH are CD8+CD69+CD103+ TRM cells that highly express PD1, CXCR3 and granzyme B; whereas liver TRM cells of patients with acute hepatitis A are mainly CD8+CD69+CD103- TRM cells that express high levels of HIF-2α." (PMID 36172356, 2022). "We have found that DPPS pretreatment significantly enhances percentages of FoxP3+ regulatory CD4+ and CD8+ cells in the livers of mice with ConA-induced hepatitis and enhances the percentage of activated CD69+CD25+ T cells, but decreases percentage of inflammatory IL-17+ and IFN-γ+ T cells." (PMID 33809904, 2021). "Constructing ConA-induced hepatitis model on Treg-depleted mice, we found that depletion of Tregs upregulated CD4+CD69+ T cells in the liver and spleen." (PMID 24981055, 2014). "Higher numbers of B cells were found in the livers of infected WT mice expressing higher levels of CD69 and CD86, suggesting that hepatic B cells could mediate the T cell response in S. japonicum infection-induced hepatitis." (PMID 34692568, 2021). "In the present study, using an established model of ConA-induced hepatitis, we demonstrate that the MDSCs are involved in T cell-mediated liver injury and that MDSC-mediated suppression of early CD4+CD69+ T cells proliferation can protect mice from ConA-induced hepatitis through ROS pathway." (PMID 24981055, 2014). "Compared with the group without postpartum hepatitis, the number of Treg in delivery woman with postpartum hepatitis was low, the ratio of CD4+ T cells expressing activated marker CD69 was significantly higher." (PMID 36685527, 2022).